CCDC141 (coiled-coil domain containing 141)
Description:
Plays a critical role in cortical radial and GnRH neurons migration during brain development. Regulates cortical radial migration by negatively controlling the activity of histone deacetylase 6 (HDAC6) and promotes centrosome maturation. CAMDI is required for dilation formation of cortical neurons during radial migration. Plays a critical role in learning and memory performance through regulation of AMPA-selective glutamate receptors (AMPARs) cell surface expression in competition with KIBRA.
Synonyms: CAMDI; FLJ39502
Tractability: PROTAC: UniProt records ubiquitination sites on it.
Gene: Protein-coding gene on chromosome 2 (178,829,757 to 179,051,697, reverse strand). Ensembl gene ENSG00000163492.
Subcellular location: Cytoplasm; Cytoplasm, cytoskeleton, microtubule organizing center, centrosome
Subcellular location (Human Protein Atlas): Nucleoplasm
Gene Ontology:
Molecular function: protein binding
Biological process: heterophilic cell-cell adhesion; regulation of synapse assembly; brain development
Cellular component: cytoplasm; plasma membrane; centrosome
Genetic constraint (gnomAD): Loss-of-function variants: 132 observed, 145.02 expected, observed/expected ratio (o/e) 0.91, 90% interval 0.79 to 1.05. The upper end of that interval is the gene's LOEUF score, 1.05, which puts it in group 4 of 6, group 1 being the genes least tolerant of losing a copy. Missense variants: 1,619 observed, 1,588.8 expected, observed/expected ratio (o/e) 1.02, 90% interval 0.98 to 1.06. Synonymous variants: 589 observed, 587.9 expected, observed/expected ratio (o/e) 1, 90% interval 0.94 to 1.07.
Homologues: Orthologues: pig CCDC141 (80% identical), rabbit CCDC141 (79% identical), mouse Ccdc141 (73% identical), dog CCDC141 (73% identical), rat Ccdc141 (72% identical), guinea pig CCDC141 (68% identical), chimpanzee CCDC141 (62% identical), Caenorhabditis elegans T21B6.3 (5% identical). Paralogues in human: OBSCN (13% identical), HMCN1 (13% identical), MYPN (9% identical), SPEG (9% identical), PALLD (9% identical), IGFN1 (8% identical), ALPK3 (7% identical), MYOT (3% identical), SPEGNB (3% identical).
Diseases named in the same sentence as CCDC141 in open-access papers:
CCDC141 is named in the same sentence as 28 diseases in open-access papers, as found by Europe PMC text mining. Sharing a sentence is not in itself a finding about the gene and the disease. The quoted sentences say what the papers report.
hypogonadotropic hypogonadism (4 papers, 2018 to 2025). Abnormal ovarian or testicular function due to insufficient hormonal stimulation from the hypothalamic-pituitary axis. "First, the association peak for the number of pregnancies and of livebirths is located within an intron of the CCDC141 gene, which is expressed in the heart and had been linked to a rare form of hypogonadotropic hypogonadism." (PMID 30188897, 2018). "Biallelic but not monoallelic variants in CCDC141 are associated with hypogonadotropic hypogonadism and hence this heterozygous variant was classified as a VUS." (PMID 36110220, 2022). "In the third patient (P89), with azoospermia and hypogonadotropic hypogonadism, a VUS in the CCDC141 gene was seen." (PMID 39180390, 2025).
Anosmia (2 papers, 2021 to 2022). An inability to perceive odors. "Thereafter, homozygous mutations of CCDC141, or heterozygous mutations in combination with mutations in other known IHH genes, were reported in Kallmann syndrome and IHH patients, although CCDC141 mutations have never previously been reported in familial self-limited delayed puberty." (PMID 34930920, 2021).
in schizophrenia 1 (2 papers, 2017 to 2022). "CCDC141 (also known as CAMDI) encodes the coiled-coil domain containing 141 protein and interacts with DISC1 (disrupted in schizophrenia 1) and MYL2 (phosphorylatable myosin light chain)." (PMID 28379579, 2017). "CCDC141 (short for coiled-coil domain containing 141), also named CAMDI after coiled-coil protein associated with myosin II and DISC1 (disrupted in schizophrenia 1), is known to affect neuronal development by impairing radial migration through DISC1 and myosin II-mediated centrosome positioning." (PMID 35350973, 2022).
cardiomyopathies (1 paper, 2023). "TTN/CCDC141 rs10497525 is an intron variant of the large sarcomeric protein, titin; variations on this gene cause muscle disorders and cardiomyopathies." (PMID 37372394, 2023).
conduction disorders (1 paper, 2018). "One SNP, rs10497529 at CCDC141 was associated (P = 5.24 × 10−7) with code I45 conduction disorders." (PMID 29769521, 2018).
Delayed puberty (1 paper, 2021). Passing the age when puberty normally occurs with no physical or hormonal signs of the onset of puberty. "Our study demonstrated that cells expressing variants identified in individuals with self-limited delayed puberty indeed had abnormal subcellular localization of these CCDC141 proteins." (PMID 34930920, 2021). "Rare, predicted deleterious variants in CCDC141 appeared enriched in self-limited delayed puberty subjects as compared to the Finnish control population, although this was not significant after FDR correction (gnomAD analysis unadjusted p-value = 0.05; FDR adjusted p value = 0.21)." (PMID 34930920, 2021).
dyslipidemia (1 paper, 2023). "TTN/CCDC141 is highly expressed in the heart, suggesting its potential role in biochemical pathways and cardiovascular health, but it has not yet been discussed under the scope of dyslipidemia and atherogenic indexes." (PMID 37372394, 2023).
migraine (1 paper, 2022). "To conclude, our study suggests that CCDC141 and VSTM2L are associated with increased risks of RLS in patients with migraine." (PMID 35350973, 2022). "By using a two-stage GWAS, we identified two novel susceptibility genes, VSTM2L and CCDC141, accountable for an increased risk of RLS in patients with migraine." (PMID 35350973, 2022). "Our data confirmed the crucial role of VSTM2L and CCDC141 in RLS in patients with migraine; however, pre-existing information regarding these two genes is scarce." (PMID 35350973, 2022). "We have used translational knockdowns (morphants), transcriptional knockdowns, and transient knockouts (crispants) in the zebrafish system to examine the functional relationship of CCDC141 and VSTM2L to the symptoms of RLS and migraine and obtained relatively consistent results." (PMID 35350973, 2022).
restless legs syndrome (1 paper, 2022). A condition that occurs while resting or lying in bed; it is characterized by an irresistible urgency to move the legs to obtain relief from a strange and uncomfortable sensation in the legs. "We identified two novel susceptibility loci rs6021854 (in VSTM2L) and rs79823654 (in CCDC141) to be associated with restless legs syndrome in migraineurs, which remained significant when compared to normal controls." (PMID 35350973, 2022). "Our GWAS and functional analysis suggest VSTM2L and CCDC141 are highly relevant to the pathogenesis of restless legs syndrome in migraineurs." (PMID 35350973, 2022).
thyroid disorder (1 paper, 2019). "Several studies show mutations in CCDC141 in patients with thyroid disorder known as idiopathic hypogonadotropic hypogonadism." (PMID 30706161, 2019).
Waardenburg syndrome (1 paper, 2022). A disorder characterized by varying degrees of deafness and minor defects in structures arising from neural crest, including pigmentation anomalies of eyes, hair, and skin. "Six new genes were associated with NSHI: INPP4B, CCDC141, MYO19, DNAH11, SOX9, and POTEI; and one new gene, PAX8, was associated with Waardenburg syndrome." (PMID 35440622, 2022).
psychiatric diseases (2 papers, 2019 to 2021). "None of the individuals carrying CCDC141 predicted deleterious variants displayed syndromic or psychiatric disorders." (PMID 34930920, 2021).
cancer (1 paper, 2012). A tumor composed of atypical neoplastic, often pleomorphic cells that invade other tissues. "We found that large portion of these gene rearrangements occur in metastatic samples; only CCDC141 showed to be overexpressed in primary cancer." (PMID 22811706, 2012).
CCDC141 also shares sentences with these, for which no sentence is quoted: atrial fibrillation (2 papers); heart failure (2); Azoospermia (1); bipolar disorder (1); Brugada syndrome (1); cognitive deficits (1); congenital hypogonadotropic hypogonadism (1); coronary artery disease (1); Duchenne muscular dystrophy (1); heart diseases (1); muscle disorders (1); neuronal migration disorders (1); Obesity (1); pituitary stalk interruption syndrome (1); Supraventricular tachycardia (1).